NF1 (neurofibromin 1)
Diseases named in the same sentence as NF1 in open-access papers (continued):
Sharing a sentence is not in itself a finding about the gene and the disease.
neurofibromatosis (continued). "Neurofibromatosis Type 1(NF-1) has autosomal dominant inheritance with complete penetrance, variable expression and a high rate of new mutation." (PMID 20219130, 2010). "Gastrointestinal stromal tumours (GIST) frequently occur in patients with neurofibromatosis type 1 (NF-1)." (PMID 19216788, 2009). "Neurofibromatosis type-1 (NF-1) is a common autosomal dominant disorder characterized by multiple neurofibromas, café-au-lait spots, freckling of the inguinal or axillary regions, gliomas, iris hamartomas, and malignant peripheral nerve sheath tumors." (PMID 15363097, 2004). "Heterozygous loss-of-function (LoF) variants in SPRED1 underlie Legius syndrome (LS, MIM: 611431), a disorder having some similarities to neurofibromatosis type I (NF1, MIM: 162200), which is caused by inactivating heterozygous mutations in NF1 (MIM: 613113), the gene encoding neurofibromin." (PMID 40362579, 2025). "Genetic mutations are detected in ≈70% of cases, and PPGL could be the first manifestation of different inherited syndromes such as von Hippel Lindau (VHL) syndrome, multiple endocrine neoplasia type 2 (MEN2), and neurofibromatosis type 1 (NF1)." (PMID 39821533, 2025). "The vast majority of PanNETs are sporadic, but approximately 17% are associated with an inherited syndrome, the most common being Multiple Endocrine Neoplasia type 1 (MEN1), von Hippel–Lindau (VHL) syndromes, Neurofibromatosis type 1 (NF1), and Tuberous Sclerosis Complex (TSC)." (PMID 38893191, 2024). "Both Neurofibromatosis type 1 (NF1) and Noonan syndrome (NS) are RASopathies." (PMID 38739321, 2024). "When examining patients with NF1 missense variants, pulmonary artery stenosis and Noonan Syndrome clinical characteristics are commonly present as opposed to the neurofibromatosis clinical picture in patients with NF1 truncating variants." (PMID 39104744, 2024). "The NF1 gene variant NM_001042492.2(NF1):c.4691_4698delinsGGCCCTCCC was discovered in the patient with B-cell lineage ALL without clinical neurofibromatosis symptoms, and this indel variant was reported neither in COSMIC nor ClinVar." (PMID 37189588, 2023). "Neurofibromatosis is a disease of haploinsufficiency or inadequate Nf1 function." (PMID 37760547, 2023). "To evaluate the role of genetic factors other than NF1 in the onset of Moyamoya in Neurofibromatosis patients, we re-sequenced the entire coding region, including the intron–exon boundaries of RNF213, the major susceptibility gene for MMD in the three groups of patients." (PMID 36980803, 2023). "Neurofibromatosis type 1 (NF-1) is the most common neurocutaneous syndrome." (PMID 37323322, 2023). "Additionally, three heterogeneous disorders make up the definition of NF, which are neurofibromatosis type 1 (NF1), neurofibromatosis type 2 (NF2), and schwannomatosis." (PMID 37181996, 2023). "Neurofibromatosis type 1 (NF-1) can manifest with various neurological symptoms." (PMID 36397418, 2022). "Patients were considered positive if those fields had mention of “NF1”, “Recklinghausen”, or “neurofibromatosis” (and various misspellings), unless the disease term was in close proximity to an exclusion word/phrase (e.g. “no sign of”, “screen for”, “not”, “unconfirmed”, “NF2”)." (PMID 36028856, 2022). "Neurofibromatosis comprises neurofibromatosis type 1 (NF1) and type 2 (NF2)." (PMID 33691671, 2021). "Of note, none of the patients with NF1 somatic mutations met the clinical criteria or had positive germline testing for neurofibromatosis." (PMID 34545084, 2021). "The mosaic form of neurofibromatosis type 1 (NF1) is called mosaic NF1 (MNF1)." (PMID 33853649, 2021). "The primary reason cited explicitly by oncologists in their clinical notes for their choice to use a novel drug was genomic results identified through molecular diagnostics or inferred based on clinical diagnosis in the case of NF1 in neurofibromatosis (N = 44, 33.1%)." (PMID 33939320, 2021).
neurofibromatosis (continued). "A 47-year-old male patient with known neurofibromatosis type 1 (NF-1) presented in May 2020 with progressive ataxia." (PMID 33905054, 2021). "Furthermore, both NFNS and WS exhibit reduced expressivity of pathognomonic NF1 features (e.g., Lisch nodules, neurofibromatosis, and internal tumors) as compared to classic NF1." (PMID 32107864, 2020). "There was no family history of NF1 and his two brothers have no stigmata at all of neurofibromatosis, suggesting that a de novo NF1 mutation occurred in the proband." (PMID 32533764, 2020). "Pancreatic neuroendocrine tumors (PNETs) account for 1 to 2% of all pancreatic tumors and most of them are sporadic and non-functioning, 5–7% arise within inherited syndromes, including MEN1, Von-Hippel Lindau (VHL) syndrome, neurofibromatosis type 1 (NF1), and tuberous sclerosis." (PMID 33384663, 2020). "Additionally, the number of patients with NF1-related MPNST can be underestimated due to underreporting or underdiagnosis of neurofibromatosis." (PMID 33003503, 2020). "Perhaps most surprising was the finding of a homozygous NF1 variant (NM_001128147.2:c.586 + 5G>A) in a young child with juvenile myelomonocytic leukemia but the parents did not have any manifestations of neurofibromatosis." (PMID 32552793, 2020). "A retrospective chart review between 2014–2018 of female NF1 patients seen at the Elizabeth Raab Neurofibromatosis Clinic (ERNC) in Ontario was conducted to examine the uptake of high-risk breast cancer screening, radiologic findings, and breast cancer characteristics." (PMID 31121919, 2019). "This may reflect the large referral base of the BCH Multidisciplinary Neurofibromatosis Program as similar studies conducted at major university hospitals have also reported a high prevalence of NF-1 and optic gliomas among boys with CNS-CPP." (PMID 29949619, 2018). "The regulation of NF1 by other miRNAs was already demonstrated in neurons and other tissues, and is considered a mechanism of fine-tuning in neurological disorders such as neurofibromatosis." (PMID 29813068, 2018). "Gender-based differences in disease onset in murine models of malignant peripheral nerve sheath tumor (MPNST) and in patients with Neurofibromatosis type-1-(NF-1)-associated or spontaneous MPNST has not been well studied." (PMID 25398666, 2014). "Hemophilia (FVIII, FIX), breast cancer (BRCA2), neurofibromatosis type I (NF1), etc." (PMID 24062987, 2013). "The synchronous diagnoses of these neural crest derived tumor entities in a patient without neurofibromatosis lends credence to the view that when these two lesions occur in patients with NF-1, the association is coincidental." (PMID 15363097, 2004). "Pheochromocytomas may manifest either as sporadic instances or as components of hereditary syndromes, such as Multiple Endocrine Neoplasia type‐2 (MEN‐2), Von Hippel–Lindau syndrome (VHL), and Neurofibromatosis type‐1 (NF‐1), depending on their prevalence and frequency of occurrence." (PMID 40062309, 2025). "Similarly, other studies have described the presence of NF1 germline variants in PPGL patients without neurofibromatosis." (PMID 39596125, 2024). "While in the classic neurofibromatosis phenotype biallelic NF1 mutations in CALM lesions were associated with a complete loss of NF1 expression, in the two patients with 3bp deletion NF1 (for whom we had unaffected skin samples for comparison) there was a commensurate reduction in NF1 expression." (PMID 39355740, 2024). "However, in our case report, the patient had no neurofibromatosis symptoms due to germline NF1 gene variants." (PMID 37189588, 2023). "Hence, in this study, we reported an NF1 gene pathogenic variant in B-cell lineage ALL in patients with no clinical neurofibromatosis symptoms." (PMID 37189588, 2023). "Bi-allelic NF1 loss of function may be a contributing factor to relapse and with sensitivity to MEK inhibitors, suggests a novel precision medicine target in the setting of neurofibromatosis patients with B-ALL." (PMID 35515133, 2022).
neurofibromatosis (continued). "The patient with NF1 variant does not have features of neurofibromatosis." (PMID 31666924, 2019). "Neurofibromin 1 (NF1), tuberous sclerosis complex (TSC1/TSC2), and phosphatase and tensin homolog (PTEN) are genes associated with neurological diseases with common autistic symptoms including neurofibromatosis, tuberous sclerosis, and Cowden/Lhermitte-Duclos syndrome." (PMID 23935565, 2013). "It is unusual for any implant to become infected after such a prolonged period and could possibly be a consequence of NF-1, since patients with neurofibromatosis are thought to be prone to infections because of a compromised immune system resulting from mast cell infiltration around neurofibromata." (PMID 21569290, 2011). "Neurofibromatoses are a class of autosomal dominant diseases, divided into Neurofibromatosis type 1 (NF1; OMIM 162200), Neurofibromatosis type 2 (NF2) and Schwannomatosis." (PMID 40402550, 2025). "Gradually, the differences in clinical presentation from NF1, led to the labelling of NF2-SWN as bilateral acoustic or central neurofibromatosis based primarily on work at the National Institutes of Health (NIH) in Maryland USA." (PMID 41160189, 2025). "There were no reported features consistent with neurofibromatosis (OMIM #162200), a highly penetrant tumor predisposition syndrome caused by pathogenic variants in NF1." (PMID 41300834, 2025). "Conversely, for KIT/PDGFRA WT cases with clinical features of a genetic disease, the multigene second-level panel could help to characterize the NF1-related GIST and to make a diagnosis of neurofibromatosis genetic disease." (PMID 41407759, 2025). "Schwannomatosis or neurilemmomatosis are multiple schwannomas without other stigmata of neurofibromatosis NF-1 and NF-2." (PMID 40337438, 2025). "The lack of a medically confirmed diagnosis of NF1 in a parent as a hereditary disease sometimes leads to situations where neurofibromatosis is only recognized at the time a child is diagnosed." (PMID 41568336, 2025). "Even without clinical signs of neurofibromatosis type 1 (NF-1), the research emphasizes the need to evaluate MTTs as a differential diagnosis for individuals presenting with tumors in the head and neck area." (PMID 39385882, 2024). "In our study, only two out of four patients positive for NF1 variants had unilateral PCC and neurofibromatosis, and none developed metastatic disease." (PMID 39596125, 2024). "In this regard, two recent studies describe the presence of pathogenic germline variants in both NF1 and SDHD genes in patients with multiple PPGLs, one of whom had no clinical sign of neurofibromatosis type 1 (NF1; MIM #162200)." (PMID 36760809, 2022). "We discuss the case of a female patient that presented with primary MPNST that arose in the urethral tract in the absence of neurofibromatosis type 1 (NF1) or prior malignancies." (PMID 36654587, 2022). "After further evaluation, 101 records were excluded due to male sex, the lack of NF1 diagnosis, benign breast disease, review article, duplicate data, neurofibromatosis type 2, and non-primary breast cancer." (PMID 30962859, 2019). "The purpose of the present study was to examine the association between retinal nerve fiber layer (RNFL) thickness measured using OCT and optic nerve function in children with OPG with and without neurofibromatosis-1 (NF-1)." (PMID 30619059, 2018). "In a Japanese death certificate study, mean age at death from neurofibromatosis was 43 years, but NF1 and NF-2 were not clearly separated." (PMID 21542925, 2011).
neurofibromatosis (continued). "The Response Evaluation in Neurofibromatosis and Schwannomatosis (REiNS) International Collaboration's Patient‐Reported Outcomes (PRO) working group has systematically reviewed and published consensus guidelines for QoL endpoints in NF1, NF2, and schwannomatosis trials." (PMID 40510571, 2025). "However, it is unlikely that the few NF2 individuals that might have been misclassified as NF1 have impacted the results, as NF2 overall constitutes only a fraction of all patients with neurofibromatosis." (PMID 37490289, 2023). "The existence of neurofibromatosis-associated diffuse lung disease (NF-DLD) as a separate entity has always been questioned and, is often attributed to cigarette smoking, rather than a manifestation of NF-1." (PMID 32742882, 2020). "Exceptionally, lack of NF1 expression has been observed in a sporadic schwannoma from a patient without neurofibromatosis, suggesting that NF1 might be a novel driver in spinal schwannoma." (PMID 33193598, 2020).
breast cancer (224 papers, 2003 to 2026). A primary or metastatic malignant neoplasm involving the breast. "A two-fold increased risk of breast cancer was observed in women with NF1 (hazard ratio (HR) 1.94, 95% confidence interval (CI) 1.59-2.36)." (PMID 41643480, 2026). "Neurofibromatosis type 1 (NF1) is a rare autosomal dominant disorder associated with an increased risk of cancer, including a 5-fold higher incidence of breast cancer." (PMID 41487701, 2026). "Despite the inherent limitations related to sample size, the principal strength of this study lies in its novelty, representing the first detailed clinical assessment of radiation therapy outcomes in patients with NF1-associated breast cancer." (PMID 41487701, 2026). "Cumulative risk for contralateral breast cancer risk is reported to be elevated in pathogenic NF1 variant carriers, estimated at 26.5% over 20 years." (PMID 41528496, 2026). "A study on NF1-deficient ER+ breast cancer revealed that NF1 loss drives metabolic reprogramming, leading to impaired oxidative ATP production, increased glutamine flux into the TCA cycle, and an expansion of lipid pools." (PMID 40244377, 2025). "It is known that women with NF1 have a higher risk of developing breast cancer, as demonstrated in our case." (PMID 40691558, 2025). "While some complications arising in individuals with NF1 are associated with a younger age, others are more commonly encountered in adulthood (e.g., MPNSTs, cardiovascular problems, GISTs, breast cancer)." (PMID 39264447, 2025). "In early-stage ER+ breast cancers, the frequencies of Nf1 mutations and copy number loss are 4% and 20%, respectively." (PMID 41000773, 2025). "This predisposes individuals with NF1 to a range of benign and malignant tumour types including gastrointestinal, ovarian, bone and breast cancers." (PMID 38859614, 2025). "As the risk for breast cancer of the general and the NF1 population converges with increasing age, breast imaging above the age of 50 years should be performed according to the same guidelines as for the general population." (PMID 39264447, 2025). "Studies have shown that patients with NF1 are predisposed to several types of malignant neoplasms, including breast cancer." (PMID 40691558, 2025). "Women with NF1 have an up to 5-fold increased risk of breast cancer before the age of 50, and an overall 3.5-fold increased risk of breast cancer." (PMID 40649916, 2025). "Loss of function of NF1 is a mechanism of acquired resistance to endocrine therapy in breast cancer." (PMID 40717978, 2025). "Neurofibromatosis type 1 (NF1) is a genetic disorder associated with an increased risk of various cancers, including breast cancer." (PMID 40691558, 2025). "Recent findings suggest that women with NF1 under the age of 50 have up to a fivefold increased risk of developing breast cancer compared to the general population." (PMID 40691558, 2025). "Awareness is a shared experience, whereby healthcare professionals’ knowledge of the condition and associated breast cancer risks is critical in aiding breast cancer awareness in women with NF1." (PMID 38859614, 2025). "In six of eight papers higher risk for earlier breast cancer was diagnosed in woman with NF1,47, 49, 50, 52, 54, 77 the other two papers report the higher risk of developing any type of cancer." (PMID 38686623, 2024). "For example, NF1 was recognized as both a tumor suppressor and fusion gene and was present within the ’Known hallmark of breast cancer’ and ’Top 20 mutated genes in breast cancer’ categories." (PMID 39472583, 2024). "The NF1 gene has been shown to be a causative agent of breast cancer, with somatic mutations reported in 27.7% of all breast carcinomas." (PMID 38673061, 2024). "These newly characterized roles of Nf1 bring us closer to answering the clinically relevant question of why NF1 patients have an increased risk of developing breast cancer with poorer prognosis compared to the general population." (PMID 38799507, 2024).